RET (ret proto-oncogene)
Diseases named in the same sentence as RET in open-access papers (continued):
Sharing a sentence is not in itself a finding about the gene and the disease.
cancer (continued). "Despite the promise of personalized therapy for RET-associated cancers, the longer term effects of RET inhibition in mature normal tissues will need to be carefully considered." (PMID 30666215, 2018). "The effects of RET mutations in familial and sporadic cancers and further details of specific genotype-phenotype correlations have been well documented in recent reviews." (PMID 30666215, 2018). "A number of other multikinase TKIs (e.g., ponatinib, alectinib, sorafenib, lenvatinib, RXDX-105) are currently in clinical trials or early preclinical testing for RET-associated cancers." (PMID 30666215, 2018). "Mutations of the RET proto-oncogene enable the kinase receptor to activate a plethora of signaling pathways related to cancer." (PMID 28122586, 2017). "Genetic variants of the proto-oncogene RET have attracted much research attention in recent studies of cancer causation." (PMID 29131865, 2017). "Our aim was to analyse the whole-gene expression profile of MTC with regard to the type of RET gene mutation and the cancer genetic background (hereditary vs sporadic)." (PMID 28181547, 2017). "This implies that miR-182-mediated blocking of HES1 expression is responsible for the activation of metastatic traits in RET oncogene-dependent cancers, since loss of this transcription factor leads to a higher invasive potential of the cells." (PMID 28122586, 2017). "The oncogenic activation of the RET gene is recognised as an early pathogenic event in cancers, and this occurrence subsequently induces the downstream signalling events involving the MEK/ERK-, PI3K/AKT-, and phospholipase Cγ- (PLCγ-) dependent pathways." (PMID 27092013, 2016). "Inherited mutations in oncogenes, which can be predisposed to cancer, have only been reported on missense mutations of the RET proto-oncogene for multiple endocrine neoplasia type 2A cancer syndrome." (PMID 27121310, 2016). "RET rearrangement, genetic variants, and mutation had been found in prognostic functions of many other cancer types." (PMID 27092013, 2016). "The RET mutations identified in all of the MTC samples enhanced confidence in our approach to detect expected mutations within a given cancer type." (PMID 27245685, 2016). "The REarranged during Transfection (RET) gene codes for a single pass transmembrane tyrosine kinase (TK) receptor that is mutated in several human cancers." (PMID 26046350, 2015). "Loss of RET signaling leads to Hirschprung's disease, while RET gain of function has been implicated in various human carcinomas." (PMID 25838128, 2015). "In contrast, gain-of-function mutations leading to aberrant RET activation, are involved in a number of human cancers." (PMID 25330015, 2014). "Since RET is a receptor tyrosine kinase these mutations cause aberrant and uncontrolled signaling ultimately leading to cancer." (PMID 23876180, 2013). "The final goal of further elucidating the natural history and pathogenesis of MEN2-related tumors should be the chance to offer patients with RET germ line mutations an optimal cancer prevention and treatment program." (PMID 23093970, 2012). "The REarranged during Transfection (RET) proto-oncogene encodes for one of the first receptor tyrosine kinases (RTKs) that were found to be involved in cancer." (PMID 23056499, 2012). "A novel multitargeted tyrosine kinase inhibitor vandetanib (ZD6474, Zactima) demonstrates specific activity against mutated RET and inhibits growth of RET-transformed cancer cells." (PMID 21819606, 2011). "RAS mutations are considered weak as they are common in benign thyroid neoplasms and other cancers, whereas RET, NTRK, and ALK rearrangements, along with mutations in BRAF, EIF1AX, and the TERT promoter, are termed strong and are often associated with malignant tumors." (PMID 39744583, 2025).
cancer (continued). "We believe our preclinical data and patient cases are pertinent to the design of a future clinical trial to determine whether selpercatinib and MitoQ combination can provide a clinical benefit to patients with RET-mutated cancers." (PMID 38378752, 2024). "RET fusions are also rare in both cancer types, posing diagnostic challenges." (PMID 39061168, 2024). "Moreover, RET mutations accounted for a significantly higher proportion of mutations in cancer tissues than benign nodules (10/124, 8.06% vs. 1/58, 1.72%, p = 0.094)." (PMID 38886866, 2024). "Molecular profiling of cancers is critical for identifying individuals with RET mutations who might benefit from RET inhibitors." (PMID 38501105, 2024). "Moreover, RET variation is associated with immune cell infiltration levels and the cancer immunity cycle (CIC) activities." (PMID 38734621, 2024). "We conducted a separate analysis for the cancer-associated genes RET and MAX." (PMID 39301547, 2024). "Moreover, in Group 1, we detected and analyzed both types of variants in the RET gene, which is widely known to be associated with cancer." (PMID 39301547, 2024). "RET mutations and fusions are well established in cancers such as NSCLC and thyroid cancers." (PMID 38790167, 2024). "This compound was then evaluated in RET-associated human cancers in the LIBRETTO-001 trial." (PMID 37835559, 2023). "Multi-targeted drugs are being used in RET mutation cancers in the early stage." (PMID 36865807, 2023). "NSCLC harboring RET fusions positive would generally predict metastasis risk and poor prognosis caused by a mutation resulting in characteristic changes of formed cancer proteins and the effect of fusion partners on RET-encoded cancer proteins." (PMID 37603207, 2023). "Selpercatinib received FDA approval in 2020 for RET-associated cancers and may well become a cornerstone in the management of advanced RET-positive MTC." (PMID 37835559, 2023). "Finally, LPCs derived from iPSCs carrying the RETC634Y mutation demonstrated a positive response to the RET inhibitor pralsetinib, as evidenced by the downregulation of these cancer markers." (PMID 38132167, 2023). "However, in addition to RET somatic mutations and CNAs, other oncogenes commonly involved in cancer pathogenesis have also been investigated in sporadic MTCs." (PMID 37835559, 2023). "RET fusion-positive carcinomas were associated with aggressive and invasive behavior." (PMID 37882481, 2023). "They involve not only the RET gene, in which single and multiple point mutations, as well as small deletions/deletions–insertions are described, but also other cancer-related genes, the alteration of which has been reported either alone or in association with the RET/RAS drivers." (PMID 35454858, 2022). "Activating RET fusions or mutations drive oncogenic signaling in lung, thyroid, and other cancers." (PMID 35304457, 2022). "Somatic RET gene activating mutations are present also in a variety of cancer, including desmoplastic melanoma (20%), cutaneous squamous cell carcinoma (10%), melanoma (6.6%), colorectal carcinoma (3.6%–6.9%), breast cancer, urothelial carcinoma, or paraganglioma." (PMID 36358717, 2022). "Moreover, we show that abnormal expression of RET in the mammary epithelium during the transition to involution causes a defect in the post-lactation process, leading to cancer predisposition." (PMID 35044452, 2022). "Drugs able to inhibit RET have been used to treat RET-mutated cancers." (PMID 36091144, 2022). "Aberrant activation of the RET proto-oncogene is implicated in a plethora of cancers." (PMID 36091144, 2022). "They used the GAL4/UAS expression system in a thyroid-linked cancer study, concluding with an unknown pathway of RET fusion activation." (PMID 36003330, 2022).
cancer (continued). "The emergence of these acquired MAPK pathway mutations suggests that later lines of therapy for RET-driven cancers may require strategies combining next-generation RET inhibitors with inhibitors targeting specific nodes in the MAPK pathway." (PMID 35304457, 2022). "RET gene mutations and fusions are known to be gain-of-function driver events in many cancer types." (PMID 36091144, 2022). "Point mutations, RET fusions, and amplification of RET gene are observed in various cancers." (PMID 36582799, 2022). "Resistance mechanisms in RET-dependent cancers may differ depending on cell type, RET gene mutation, RET expression level, and TERT promoter mutation status." (PMID 35510953, 2022). "Additionally, studies performed over the last three decades have identified numerous alterations in RET that confer constitutive activation of its kinase activity, which is considered a causative factor in many cancer subtypes." (PMID 35957881, 2022). "It has been well established that RET, as a transmembrane protein, interacts with several tyrosine kinase proteins, and their intracellular interaction has been associated with various type of cancer cell proliferation." (PMID 34207842, 2021). "Besides the increased expression level of RET, different RET isoforms and polymorphic variants are important in cancer development and migration." (PMID 34572820, 2021). "RET has been implicated in the activation of multiple signaling pathways promoting cell cycle progression, cell proliferation, migration, survival, and differentiation, and therefore, in the pathogenesis and metastatic progression of various cancers." (PMID 34149933, 2021). "RET alterations by point mutations and gene fusions were found in diverse cancers." (PMID 35582449, 2020). "Furthermore, a significant proportion of SDHB- and RET-associated malignant tumors also showed an increase in GLS-1 staining compared to benign RET-associated and sporadic tumors." (PMID 32150977, 2020). "Few studies have shown association between RET and miRNAs in this kind of cancer." (PMID 32637757, 2020). "Oncogenic activation of RET, causing heritable and sporadic cancers, results of either activating point mutations or genomic rearrangements with the production of chimeric RET proteins that lead to its constitutive activation or through aberrant expression or activation of wild-type receptors." (PMID 31731495, 2019). "Loss or changes in the JM region of RET have been associated with cancer." (PMID 30446652, 2018). "In some familial cases where the two cancers coexist, polymorphisms in the RET gene have been speculated to act as ‘modifiers’ of RET expression." (PMID 28951487, 2017). "Moreover, many studies have investigated multifocal PTC clonality through a number of approaches, including X-chromosome inactivation, BRAF mutation, RET rearrangements, loss of heterozygosity, or allelic imbalances of distinct cancer foci." (PMID 28302162, 2017). "However, the association with RET isoforms and tumorigenic potentials in RET fusion-positive cancer is not clearly known." (PMID 27150058, 2016). "The identification of these mutations and rearrangements in RET which lead to constitutive activation, together with convincing preclinical data validating RET as a classical oncogene, make this kinase an attractive target for cancer therapy." (PMID 26874741, 2016). "All five of the cancers assayed in this study had activating mutations in RET." (PMID 27245685, 2016). "Recently, trans RET signaling has been implicated in the development of inhibitory cortical interneurons, nigral dopaminergic neurons, and enteric lymphoids, and in perineural invasion by cancer cells." (PMID 25838128, 2015). "The RET gene undergoes oncogenic activation through mutation or cytogenetic rearrangement in many tumors, but its role in cancer pathogenesis remains unknown." (PMID 25720956, 2015).
cancer (continued). "The Y791F variant in the RET protooncogene was further present in another centenarian with a history of cancer of unknown origin." (PMID 25333069, 2014). "Interestingly, in hereditary MTC, recent data suggest that specific germline RET mutations are associated with age-specific penetrance of cancer development and lymph node metastases." (PMID 20069043, 2009). "Selpercatinib improves outcomes in Rearranged during Transfection (RET) fusion-positive non-small cell lung cancer (NSCLC) but can rarely cause chylous ascites (CA)." (PMID 41346910, 2025). "Yet, contrasting findings have emerged from a recent study suggesting that RET mutations might actually offer a positive predictive response to ICI therapy, proposing that RET translocations and RET point mutations may trigger distinct molecular pathways in cancer." (PMID 38317126, 2024). "Hence, the RETC634Y mutation appears to be linked to the upregulation of cancer-related markers and may be associated with a delay in the differentiation process, which is a characteristic feature of RET-driven NSCLC." (PMID 38132167, 2023). "Furthermore, cancer-causing mutations in any of Ret Proto-oncogene (RET), neurotrophic tyrosine receptor kinase (NTRK), RAS, B-Raf proto-oncogene (BRAF), or telomerase reverse transcriptase (TERT) gene are linked to loss of thyroid-differentiating genes, including NIS." (PMID 35634509, 2022). "The advent of high-throughput technology has identified cancers with rare RET alterations beyond point mutations and fusions, including RET deletions, raising questions about whether these alterations have a functional effect and can be targeted by RET inhibitors." (PMID 36091144, 2022). "Moreover, the increasing use of NGS has uncovered RET mutations in a variety of cancers, including endometrial and ovarian cancers, hepatomas, skin melanomas, glioblastoma multiforme, meningiomas, gastrointestinal stromal tumors, Merkel cell carcinomas, paragangliomas, and atypical lung carcinoids." (PMID 33150251, 2020). "The oncogenic mutations in this domain may induce conformational changes in proteins, which decrease autoinhibition, increase kinase activity and ATP binding, generate a better intermolecular substrate, and then cause the autophosphorylation of RET to induce cancer." (PMID 32293499, 2020). "For instance, structurally conserved RET-M918T and MET-M1250T cancer drivers are situated in the substrate binding C-lobe of the kinase core and are known to be associated with oncogenic activation by displaying the highest transforming potential among known RET and MET mutations." (PMID 19834613, 2009). "Because of the roles of RET in the development and progression of these cancers, RET has been an important target for therapeutic intervention." (PMID 40725174, 2025). "Selpercatinib, a highly selective RET kinase inhibitor with CNS activity, was developed specifically to treat patients with RET-altered cancers." (PMID 41465387, 2025). "Of the fusion genes that have matched FDA-approved targeted therapy in at least one cancer, only RET and NTRK1/2/3 have FDA approvals that are tumor type–agnostic." (PMID 41091579, 2025). "The same mechanisms of resistance have been observed across multiple cancer types, which implies RET-altered cancers evolve away from RET addiction via stochastic subclonal events." (PMID 39655713, 2025). "This innovative approach has revolutionized the treatment of RET‐altered cancers, offering new hope and improved outcomes on patients with RET‐altered cancer." (PMID 40237476, 2025). "This strong genotype–phenotype relationship has driven the search for RET kinase inhibitors for treating RET-altered cancers." (PMID 39655713, 2025). "The development of selective RET inhibitors like selpercatinib and pralsetinib has marked a significant advancement in targeting RET-driven cancers." (PMID 39925808, 2025).
cancer (continued). "In conclusion, our study underscores the importance of the combined targeting of RET and EGFR to overcome resistance mechanisms in RET-rearranged cancers." (PMID 40405293, 2025). "The objective response rates to selective RET inhibitors in RET-altered cancers are very high, reaching 64–70%, thus underscoring the importance of RET testing." (PMID 41373459, 2025). "Most patients in this update had GI RET-positive cancers (n = 31), with pancreatic and colorectal being the most common." (PMID 41179283, 2025). "For this cohort, U-grading and genetics were discordant, with RET gene testing more effective than ultrasound in cancer detection." (PMID 39555152, 2025). "Though the development and increasing usage of selpercatinib improved survival of patients with RET‐altered cancer, it is crucial to be aware of its adverse events (AEs)." (PMID 40237476, 2025). "Due to the more aggressive cancer phenotype, RET fusions in PC require deeper analyses, primarily a surveillance of the response in a larger patient population." (PMID 41374970, 2025). "A total of 316 patients (21.1%) had a fusion detected (RET or NTRK1/2/3) with matched targeted therapy approved in all cancer indications." (PMID 41091579, 2025). "While the drugs targeting PD-1 BRAF V600E and RET fusion for pan-cancer treatment is considered as an expansion of the existing drugs for pan-cancer, Vitrakvi® targeting NTRK is a drug truly developed for pan-cancer treatment." (PMID 41294857, 2025). "Because the RET receptor is essential for hunger, weight gain management, and the survival and maintenance of multiple sclerosis, its important to inhibat RET enzyme to decrease disease spreading specially cancer diseases." (PMID 39985107, 2025). "Highly selective RET inhibitors have improved outcomes in RET-altered cancers and have been well-tolerated." (PMID 39655713, 2025). "Cancer cells with RET/PTC1 rearrangements rely more on the RAF‐1 pathway for survival and growth than on the BRAF‐ERK pathway, which is typically needed in cells with RAS or BRAF mutations." (PMID 40911853, 2025). "While RET (REarranged during Transfection) fusions are comparatively uncommon across various human cancers, their identification is of paramount clinical significance." (PMID 41373459, 2025). "We investigated the ROS1 and RET fusions concerning mutation rates in the CRC (MSK, JNC 2021) study from the cBioPortal for cancer genomics database." (PMID 40572720, 2025). "Aberrant alterations in the RET gene serve as oncogenic drivers in multiple cancers, making RET kinase inhibition a promising therapeutic strategy." (PMID 41181595, 2025). "Selpercatinib and pralsetinib have been approved by the FDA for treating RET-altered cancers, demonstrating high response rates in clinical trials." (PMID 39925808, 2025). "Fourteen genes, including RET, were found to be part of the canonical fusions targeted by 36 drugs in 21 different cancers." (PMID 41246330, 2025). "Rearranged during transfection (RET) is a single‐pass receptor tyrosine kinase, and alterations in RET gene are involved in the pathogenesis of several cancer types." (PMID 40237476, 2025). "RET-altered cancers utilize gatekeeper mutants as a mechanism of resistance to treatments, as seen in RETV804M/L." (PMID 41179283, 2025). "Proteins like RET (enriched in JAK-STAT signaling) and FGFR3 (linked to pathways in cancer) are already targeted by approved therapies in other malignancies, suggesting rapid repurposing potential for PCa." (PMID 41247789, 2025). "Further studies are warranted to evaluate HA121-28 and its combination with other active drugs in cancer patients with RET-fusion." (PMID 40016191, 2025). "Hopefully, with future research and further identification of resistance mechanisms selective RET, TKIs will continue to improve outcomes in RET-altered cancers." (PMID 40332427, 2025).